CGA (glycoprotein hormones, alpha polypeptide)
Diseases named in the same sentence as CGA in open-access papers (continued):
Sharing a sentence is not in itself a finding about the gene and the disease.
type 2 diabetes (5 papers, 2020 to 2026). "In patients with type 2 diabetes, the high levels of salivary CgA are associated with periodontal damage." (PMID 34204153, 2021). "Chromogranin A (CgA) is a pro-hormone widely expressed in neuroendocrine tissues and elevated in both type 1 (T1D) and type 2 diabetes (T2D)." (PMID 42051247, 2026). "Circulating levels of CgA and pancreastain are high in type 1 and type 2 diabetes, respectively, because CgA is one of pathogeneses of type 1 diabetes, and pancreastatin induces insulin hyposecretion and insulin resistance." (PMID 34204153, 2021). "The presence of underlying type II diabetes was significantly associated with increased concentrations of CST (2.36 [1.19; 5.06] ng/mL vs 1.41 [0.80; 2.76], p=0.036); admission glycaemia correlated with CgA only in ICU+COVID+ patients (Spearman rho=0.284, n=49, p<0.05)." (PMID 36248786, 2022). "Therefore, CgA in saliva may be a biomarker for oral health in patients with type 2 diabetes." (PMID 34204153, 2021). "Higher levels of CgA in the circulating blood have been reported in patients with type 1 diabetes, but not those with type 2 diabetes, when compared with control subjects." (PMID 34204153, 2021). "Neither serum CgB levels (p = 0.1698), nor CgA levels (p = 0.1587) of all type 2 diabetes patients differed from those of their matched controls." (PMID 32684986, 2020). "We have demonstrated that neither CgA nor CgB level differed in type 2 diabetes patients from those in healthy controls, but serum CgB level was lower in the subgroup of type 2 diabetes patients with ICT." (PMID 32684986, 2020).
adenoma (4 papers, 2011 to 2025). A neoplasm arising from the epithelium. "On the contrary, some studies suggested that cortisol-secreting adenomas had higher blood CgA values." (PMID 41007858, 2025). "In contrast with the NRP-1 staining pattern which altered markedly in adenoma by comparison with normal tissue, the CgA staining remained limited to singly dispersed cells." (PMID 21401950, 2011). "Our data examining the expression pattern of NRP-1 and CgA in adenomas show that, whereas there are similarities and overlaps in morphologically normal tissue, the regulation of the two markers becomes profoundly unlinked in adenomas." (PMID 21401950, 2011). "Adjacent adenoma sections were concomitantly stained with CgA." (PMID 21401950, 2011). "Focusing on the promoter methylation status of the neuroendocrine markers chromogranin A (CgA), chromogranin B (CgB) and CD56 (NCAM1) confirmed congruently lower methylation levels in NETs and PitNETs/adenomas compared to adenomas." (PMID 41060331, 2025).
colon cancer (4 papers, 2014 to 2022). "Reduced staining for CGA+ neuroendocrine and lysozyme+ Paneth differentiated cells was found in colonic tumor tissue in comparison to normal colon." (PMID 35743243, 2022). "According to our previous study, the LoVo colon cancer cell line was selected, and CgA was successfully overexpressed to construct neuroendocrine differentiated colon cancer cells, namely, LoVo-CgA cells." (PMID 36030223, 2022). "Based on these literatures, we assumed that colon cancer cells could be transformed into neuroendocrine cells by overexpressing the neuroendocrine differentiation markers CgA and Syn." (PMID 27034164, 2016). "Notably, neither lysozyme nor CGA staining was observed in the neoplastic epithelium in colonic tumor tissue, but staining was observed within the stroma." (PMID 35743243, 2022).
gastric cancer (4 papers, 2022 to 2024). A primary or metastatic malignant neoplasm involving the stomach. "The differences in positive rates of chromogranin A (CgA) and Ki-67 were analyzed by univariate Cox regression analysis as independent risk factors that may affect the survival of gastric cancer patients." (PMID 36035314, 2022). "Despite this, research into CGA’s role in gastric cancer has been limited, primarily confirming its presence in neuroendocrine differentiated entities within diffuse gastric carcinomas." (PMID 39588299, 2024). "In this study, we found that the positive rates of CgA in the three groups of gastric cancer patients were 68.75%, 87.5%, and 78.57%, respectively." (PMID 36035314, 2022). "Therefore, we examined the two gastric cancer cells for ECL markers chromogranin A (CgA) and synaptophysin (Syn) by immunocytochemistry and immunofluorescence, and negative staining was observed for CgA and Syn in both SGC-7901 and AGS cells." (PMID 34976177, 2022). "Univariate analysis showed that the expression of CgA and Syn was not related to OS, suggesting that the prognosis of gastric cancer patients with neuroendocrine differentiation was not affected by the expression of neuroendocrine markers CgA and Syn." (PMID 36035314, 2022).
liver disease (4 papers, 2021 to 2024). "Whereas CgA is of prognostic value for intra- and extra-hepatic disease, GGT has only been evaluated for liver tumor burden." (PMID 37770647, 2024). "As a possible explanation, liver enzymes and CgA are suspected to increase via radiation therapy-induced liver disease, which typically presents after 4–8 weeks of initial treatment administration." (PMID 38136263, 2023). "Higher levels of CgA were observed in NET patients with diffuse disease compared to those with local or hepatic disease, and those that were disease-free." (PMID 34868938, 2021).
Merkel cell carcinoma (4 papers, 2020 to 2025). "Among the three cases of merkel cell carcinoma, 2 cases were negative for CgA immunolabeling and 1 case was positive." (PMID 41245381, 2025). "Paranuclear dot-like staining for CgA, CK20 and Neurofilament (NF), and polyomavirus stain, may also help in the identification of neuroendocrine skin lesions such as Merkel cell carcinomas (MCCs)." (PMID 37685605, 2023).
multiple myeloma (4 papers, 2012 to 2022). "Studies on the mechanism of action revealed that multiple myeloma and endothelial cells can promote CgA cleavage through the activation of the plasminogen activator/plasmin system." (PMID 36559048, 2022). "The studies performed in patients with multiple myeloma have shown that CgA is cleaved into the proangiogenic form CgA1-373 in the bone marrow and that, consequently, the ratio of pro-/anti-angiogenic forms of CgA is higher in patients compared to healthy individuals." (PMID 36559048, 2022).
non-small cell lung carcinoma (4 papers, 2016 to 2025). A group of at least three distinct histological types of lung cancer, including non-small cell squamous cell carcinoma, adenocarcinoma, and large cell carcinoma. "Anti-CgA autoantibodies can be found for example in non-small cell lung cancer patients; however, there is a strong bulk of evidence that CgA may play a role as an autoantigen in the pathogenesis of type 1 diabetes (T1DM)." (PMID 40370467, 2025).
pancreatic adenocarcinoma (4 papers, 2016 to 2025). "Another was diagnosed with pancreatic adenocarcinoma and underwent pancreaticoduodenectomy (the tail and body of the pancreas had been resected previously because of panNETs), and CgA normalized after surgery." (PMID 40455177, 2025). "Patients with pancreatic adenocarcinomas have also been reported to show higher CgA levels than healthy individuals." (PMID 34943638, 2021).
pancreatic neuroendocrine neoplasm (4 papers, 2014 to 2023). A neoplasm with neuroendocrine differentiation that arises from the pancreas. "Whether thrombosis or CgA level is associated with risk of poorly differentiated pancreatic neuroendocrine neoplasms should be investigated in future studies." (PMID 38087239, 2023). "In that study, the authors enrolled a total of 181 GEP-NEN patients, including 81 pancreatic NEN, and have shown the significant prognostic relevance of plasma CgA." (PMID 37510802, 2023).
Parkinson disease (4 papers, 2020 to 2023). A progressive degenerative disorder of the central nervous system characterized by loss of dopamine producing neurons in the substantia nigra and the presence of Lewy bodies in the substantia nigra and locus coeruleus. "Recent studies show that CgA levels may also be altered in patients with Parkinson’s disease (PD), in both serum and cerebrospinal fluid (CSF)." (PMID 33499181, 2021).
preeclampsia (4 papers, 2021 to 2025). Preeclampsia is a hypertensive disorder of pregnancy that is characterized by new-onset hypertension with proteinuria presenting after 20 weeks of gestation, and depending on mild or severe forms may initially present with severe headache, visual disturbances, and hyperreflexia. "We also observed high DMC density regions in genes for which placental DNAm and/or expression differences have been associated with preeclampsia, including INHBA, JUNB, TEAD3, NDRG1, and CGA." (PMID 33407091, 2021).
adrenal adenoma (3 papers, 2019 to 2025). "Other researchers showed higher plasma CgA in patients with an adrenal adenoma than in subjects without one, which may underlie a slightly higher unadjusted Cts in our AI patients than controls." (PMID 37522122, 2023). "Other researchers, however, did not discover any connection between adrenocortical adenomas and high serum CgA concentrations, even when the tumors were stained with the protein using immunohistochemistry." (PMID 41007858, 2025). "Since CgA is not expressed in the adrenocortical adenoma tissue, Cts levels are unlikely to differ between subjects with and without an adrenal adenoma, which is what we found here for AI patients compared to age-, sex-, and BMI-matched controls after adjusting for confounding factors." (PMID 37522122, 2023).
adrenocortical tumors (3 papers, 2001 to 2025). "Because it is not expressed at the immuno-histochemical level and has not been related to noticeably increased plasma levels associated with adrenocortical tumors, CgA does not appear to be involved in cortical carcinogenesis, according to multiple studies." (PMID 41007858, 2025).
colorectal cancer (3 papers, 2014 to 2020). A primary or metastatic malignant neoplasm that affects the colon or rectum. "Based on our results we propose a new subtype of colorectal cancer, which can be characterized by CgA+ differentiation, therefore we suggest the routine usage of CgA-specific immunohistochemical staining of colorectal tumor specimens." (PMID 33383764, 2020). "CgA and Syn are the most frequently used markers of NE cells in colorectal cancer studies." (PMID 25093184, 2014). "Several factors are known to affect colorectal cancer (CRC) patient survival, including elevated platelet counts (thrombocytosis) and chromogranin A-positive neuroendocrine-cell differentiation (CgA+)." (PMID 33383764, 2020).
large cell neuroendocrine carcinoma (3 papers, 2019 to 2025). A usually aggressive carcinoma composed of large malignant cells which display neuroendocrine characteristics. "Neuroendocrine markers Syn may be weakly positive in focal areas, thus predisposing to misdiagnosing large cell neuroendocrine carcinoma, but CgA is usually not expressed." (PMID 38989233, 2024). "In large-cell neuroendocrine carcinoma, CD56 and SYP demonstrated greater sensitivity than INSM1, whereas CgA showed lower sensitivity." (PMID 39937015, 2025).
liver failure (3 papers, 2022 to 2025). A liver disease characterized by the liver losing or has lost all of its function. "In addition, elevated CgA levels are also found in many other conditions such as renal and hepatic failure, inflammatory diseases, or following the use of proton-pump inhibitors." (PMID 35205614, 2022).
lung carcinoids (3 papers, 2020 to 2022). "Our results suggest that compared with HE, IHC is more accurate in diagnosing lung carcinoids, in particular, Syn and CgA can be used to distinguish NET from NEC." (PMID 35331190, 2022). "Lack of pepper-like nuclear chromatin, spindle cells, and plasma-like cells with eccentric nuclear, as well as negative for CgA and Syn, are used to differentiate papillary adenoma from lung carcinoid and atypical carcinoid." (PMID 33282636, 2020). "Given that CgA is normal in ∼60% of lung carcinoids, it is not surprising that it performed poorly." (PMID 32047924, 2020).
lung disease (3 papers, 2020 to 2024). "Overall, CgA was not an effective biomarker for any lung disease evaluated." (PMID 32047924, 2020).
mammary adenocarcinoma (3 papers, 2013 to 2016). "Systemic administration of full-length CgA, but not of fragments lacking the C-terminal region, could reduce tumor growth in murine models of fibrosarcoma, mammary adenocarcinoma, Lewis lung carcinoma, and primary and metastatic melanoma, with U-shaped dose-response curves." (PMID 27683038, 2016). "CgA has been identified to play a role in preventing tumor cell seeding and progression in a mouse model of breast adenocarcinoma, suggesting that elevated CgA levels (perhaps of specific fragments – this was not assessed in the study) may have an inhibitory role in neoplastic development." (PMID 24260544, 2013).
multiple endocrine neoplasia type 1 (3 papers, 2020 to 2025). An autosomal dominant tumor predisposition syndrome caused by pathogenic variants in the MEN1 gene, characterized by an increased risk of tumors of the parathyroid glands, pituitary gland, and foregut neuroendocrine tumors (most commonly pancreatic islet cells). "One malignant PPoma, Case 1, from a multiple endocrine neoplasia-1 (MEN-1) family was solid pattern with moderately and granular staining for PP and moderately for CgA at 5% of tumor cell cytoplasm and diffuse strong staining for SPY." (PMID 32020844, 2020).
Obesity (3 papers, 2017 to 2025). Accumulation of substantial excess body fat. "Elevated serum CgA levels were independently associated with insulin resistance, low-grade inflammation, and obesity, indicating its potential utility as a biomarker for metabolic dysregulation in PCOS." (PMID 41480370, 2025). "Elevated CgA levels in PCOS are independently associated with obesity, insulin resistance, and low-grade inflammation." (PMID 41480370, 2025). "In CgA knockout mice, obesity and peripheral insulin resistance coexist with improved hepatic insulin sensitivity." (PMID 41480370, 2025). "This supports the hypothesis that CgA may contribute to the regulation of metabolic homeostasis and play a role in the development of insulin resistance and obesity." (PMID 41480370, 2025).
renal cell carcinoma (3 papers, 2018 to 2024). "Pathological examination revealed morphological and immunohistochemical findings in line with metastatic renal cell carcinoma, including positive staining for AE1/AE3 vimentin and CD10, partial positive for RCC, PAX-8, and negative staining for inhibin, CgA, and CA9, the index of Ki-67 is 5%." (PMID 34397852, 2021).
type 1 diabetes (3 papers, 2020 to 2025). "CgA is known to play a significant role in the pathogenesis and development of type 1 diabetes, and is associated with its complications." (PMID 34204153, 2021). "Serum CgA level was significantly higher (p = 0.0348) in type 1 diabetes patients than that of healthy controls, in accordance with our previous reports." (PMID 32684986, 2020). "CgA is known to play a significant role in the pathogenesis and development of type 1 diabetes." (PMID 34204153, 2021). "In addition, type 1 diabetic patients have high CgA and low CgB levels in the circulating blood." (PMID 34204153, 2021). "CgA and its derivate peptides are elevated in certain autoimmune diseases such as IBD, CD, RA, SLE, or type 1 diabetes, as well as in a variety of other conditions also manifested by inflammation, thus suggesting their role in the pathogenesis of these disorders." (PMID 40370467, 2025).
atherosclerosis (2 papers, 2021). A disease characterized by the build-up of fatty material and calcium deposition in the arterial wall resulting in partial or complete occlusion of the arterial lumen. "CgA- and CgC--derived polypeptides provide the therapeutic target for atherosclerosis and ischemia-induced tissue damages." (PMID 34204153, 2021). "The in vivo effects of CgA and its derived peptides on atherosclerosis have been evaluated in murine models with their exogenous infusion and endogenous deficiency." (PMID 34204153, 2021).
bone metastasis (2 papers, 2023 to 2025). Transfer of a neoplasm from its primary site to bones. "The analysis performed in this study showed that CgA, serotonin, and 5-HIAA levels did not have the capacity to function as biomarkers for detecting bone metastasis." (PMID 37510802, 2023).
carcinoid heart disease (2 papers, 2013 to 2018). Cardiac manifestation of gastrointestinal CARCINOID TUMOR that metastasizes to the liver. "The concentration of Chromogranin A (CgA), present in the chromograffin granules of neuroendocrine cells, has also been significantly associated with the prevalence of and survival from carcinoid heart disease." (PMID 24069222, 2013). "We found a poor correlation between CgA and the severity of carcinoid heart disease which may be because CgA is falsely elevated by proton pump inhibitor (PPI) therapy in healthy individuals, and those with NETs." (PMID 24069222, 2013). "These factors may explain why we found CgB to be more sensitive and specific than CgA for carcinoid heart disease." (PMID 24069222, 2013). "Significantly higher median values of all 5 biomarkers were found in the patients with carcinoid heart disease compared to those without, (NT-proBNP 474 vs. 79 ng/L, 5HIAA 353 vs. 57 ng/ml, CgA 16 vs. 7 ng/ml, CgB 13 vs. 8 ng/ml and NkA 27 vs. 16 ng/L)." (PMID 24069222, 2013). "Thirty percent of patients who did not have carcinoid heart disease were taking PPI therapy, which undoubtedly will have influenced the CgA results." (PMID 24069222, 2013).
colorectal adenocarcinoma (2 papers, 2020 to 2022). The most common type of colorectal carcinoma. "Summarizing our pilot study, according to our results, patients with colorectal adenocarcinoma differentiated by CgA+ cells had worse survival and clinicopathological features." (PMID 33383764, 2020). "These include high platelet counts (thrombocytosis) and chromogranin A-positive neuroendocrine cell (CgA+) differentiation within the colorectal adenocarcinoma." (PMID 33383764, 2020). "The immunohistochemical sections of colorectal adenocarcinoma from 10 patients (5 from the NED group and 5 from the non-NED group) showed that tumor-associated macrophages (stained by CD68) accumulated where CgA protein was expressed." (PMID 36030223, 2022). "Despite the rising number of studies reporting a large number of CgA+ differentiated colorectal adenocarcinomas CgA+ differentiation is basically not used in its routine diagnostics." (PMID 33383764, 2020).
corticobasal degeneration (2 papers, 2024 to 2025). "Here, we investigated the role of CgA in Tau pathogenesis in AD and corticobasal degeneration (CBD)." (PMID 40393970, 2025).